RN7SL98P (RNA, 7SL, cytoplasmic 98, pseudogene)
Gene: Miscellaneous RNA gene on chromosome 9 (15,525,782 to 15,526,081, reverse strand). Ensembl gene ENSG00000240613.
Homologues: Orthologues: chimpanzee Metazoa_SRP (100% identical), macaque Metazoa_SRP (93% identical), dog Metazoa_SRP (57% identical). Paralogues in human: RN7SL1 (79% identical), RN7SL2 (79% identical), RN7SL127P (78% identical), RN7SL3 (78% identical), RN7SL566P (77% identical), RN7SL712P (77% identical), RN7SL113P (77% identical), RN7SL220P (77% identical), RN7SL296P (77% identical), RN7SL239P (77% identical), RN7SL304P (77% identical), RN7SL732P (77% identical), and 700 more.